NOX1 (NADPH oxidase 1)
Diseases named in the same sentence as NOX1 in open-access papers (continued):
Sharing a sentence is not in itself a finding about the gene and the disease.
colitis (continued). "In addition, mice models that were deficient in NOX1 had lowered levels of LCN-2 production and colon damage during TNBS-induced colitis." (PMID 34603464, 2021). "Nox1, Nox2 and Nox4 mRNA expression levels were all elevated in experimental colitis." (PMID 32945118, 2020). "Nox1-deficient (Nox1KO) mice show a massive conversion of progenitor cells into functional goblet cells without developing any colitis." (PMID 25014110, 2014). "As TNFα-induced colitis was accompanied by a substantial increase in expression of the NOX1 subunits and an infiltration of neutrophils which could release large amount of ROS via NOX2, we next examined oxidative stress markers in the colon." (PMID 25276054, 2014). "The observation that the expression of NOX1, NOXA1, NOXO1, and p22PHOX is increased during TNFα-induced colitis is in agreement with previous in vitro studies showing that treatment of T84 colon epithelial cells with TNFα increased NOX1 and NOXO1 expression at the mRNA and protein levels." (PMID 25276054, 2014). "Consistent with the transcriptome analysis result, the qPCR analysis results showed that the Nox1 mRNA expression in the colons of IL-4Rα-/- colitis mice was significantly higher than that in the colons of WT colitis mice (0.21 ± 0.04 in WT colitis, 2.00 ± 0.26 in IL-4Rα-/- colitis; p < 0.05)." (PMID 33192516, 2020). "Previous studies have illustrated alterations in NOX1 expression; however, the vast majority suggest that NOX2-derived ROS regulates inflammation during colitis." (PMID 37239114, 2023). "Expression of all of the subunits forming the NOX1 system, namely, NOX1, p22PHOX, NOXA1, and NOXO1, was indeed increased in the mouse model of TNFα-induced colitis." (PMID 25276054, 2014). "This study demonstrates for the first time that TNFα-induced colitis triggers a marked increase in the expression of key components of the colon-specific NADPH oxidase isoform, NOX1, NOXA1, NOXO1, and p22PHOX." (PMID 25276054, 2014). "As DUOX2 homologue of NADPH oxidase is known to be expressed in the colon, although at a lower level than NOX1, we next investigated DUOX2 expression during TNFα-induced colitis." (PMID 25276054, 2014). "It has been demonstrated in a model of TNBS-induced colitis that a rise in SOD activity inhibits the production of proinflammatory cytokines TNFα and IL-1β, which are enhancers of ROS production due to the promotion of endosomal internalization of Nox1." (PMID 40305159, 2025). "NOX1 mediated ROS injury of colonic epithelial cells in chronic DSS colitis mice, while NADPH oxidase inhibitors exerted a protective effect against the proinflammatory response of LPS in mouse colon epithelial cells during chronic DSS colitis." (PMID 35639301, 2023). "For example, TNFα, a critical driver of IEC shedding in colitis, induces superoxide generation via NOX2, NOX1 and the mitochondria, which will trigger, depending on the context, apoptosis, necroptosis, survival and further upregulation of proinflammatory cytokines such as TNFα and IL-6." (PMID 33059312, 2020). "In this study, we showed that both immunological and epithelial deficiencies in mice lacking the anti-inflammatory cytokine IL10 and Nox1 sensitized the colon to spontaneously develop severe colitis and mimicked all clinical and histological characteristics of UC." (PMID 25014110, 2014).
melanoma (19 papers, 2011 to 2025). A malignant, usually aggressive tumor composed of atypical, neoplastic melanocytes. "Overexpression of Nox1 in melanoma cells is often associated with increased migration/metastasis rate." (PMID 33451139, 2021). "NADPH oxidases are one of the main enzymatic sources of ROS in cells and the relative expression of NOX1 and NOX4was linked to melanoma cell survival." (PMID 27756874, 2016). "Overexpression of NADPH oxidase 1 (Nox1) in melanoma cells is often associated with increased migration/metastasis rate." (PMID 26760964, 2016). "Using an in vitro cell migration assay, we observed that treatment of different melanoma cell lines with honokiol for 24 h resulted in a dose-dependent inhibition of cell migration that was associated with reduction in Nox1 expression and reduced levels of oxidative stress." (PMID 26760964, 2016). "Furthermore, we ascertained that the inhibitory effect of honokiol on melanoma cell migration is mediated through the inhibition of Nox-1 and associated molecular targets." (PMID 26760964, 2016). "In addition to NOX4, uncoupled eNOS and overexpressed NOX1 also produced ROS in melanoma, linked to Epithelial–Mesenchymal Transition." (PMID 25296975, 2014). "NADPH oxidase 1 (Nox1) overexpression in melanoma cells is often connected with an elevated metastasis rate." (PMID 40943669, 2025). "In this regard, we showed that 13% of the melanoma patients have alterations on NOX1 gene, 7% on NOX2, NOX3 and NOX5, and 15% on NOX4." (PMID 35326089, 2022). "In melanomas, NOX1, NOX4, and NOX5 have been confirmed to be expressed, with NOX1 expression consistent throughout progression and NOX4 upregulated during metastasis." (PMID 35326683, 2022). "NOX1 was found to be overexpressed in melanoma cell lines, and its ability to enhance cell invasion by matrix metalloproteinase-2 upregulation and EMT induction was demonstrated." (PMID 34943045, 2021). "NADPH oxidase (Nox) activity is induced by UV radiation, and Nox1 protein levels are higher in melanoma cells than in normal melanocytes." (PMID 33451139, 2021). "NOX1 is overexpressed in melanoma cells and controls melanoma invasion by regulating matrix metaloproteinase-2 (MMP-2) transcription." (PMID 32850409, 2020). "As honokiol treatment significantly reduced migration capacity of melanoma cells, we further determined the effect of honokiol on Nox1 protein expression in melanoma cells." (PMID 26760964, 2016). "The basal level of Nox1 in NHM was detectable but to a lesser extent than observed in melanoma cell lines." (PMID 26760964, 2016). "The densitometry analysis of bands indicated that the basal levels of Nox1 in melanoma cell lines were 4 to 20-fold higher than NHM." (PMID 26760964, 2016). "Western blot analysis revealed that the melanoma cell lines (A375, Hs294, SK-Mel 119, SK-Mel 28, Mel1241, Mel1011, and Mel928) exhibited different basal levels of Nox1 expression." (PMID 26760964, 2016). "We first examined the basal level of Nox1 protein expression in different melanoma cell lines as compared with the levels in normal human melanocytes (NHM)." (PMID 26760964, 2016). "Local cross-talk exists between Cav-1, overexpressed in melanoma, and NOX1, modulating NOX1 activity." (PMID 27756874, 2016). "In general, the melanoma cell lines that have higher Nox1 activity showed a higher number of migratory cells compared to NHM." (PMID 26760964, 2016). "To this end, we implanted tumorigenic B16F0 melanoma cells or Lewis Lung Carcinoma (LLC1) cells subcutaneously into WT and NOX1-deficient mice." (PMID 21326871, 2011). "It acted as an inhibitor of NADPH oxidase 1 and melanoma cell migration." (PMID 40943669, 2025). "The expression and activity of NOX1 are increased in melanoma cells and their stages." (PMID 35326089, 2022). "Moreover, the specific NOX1 inhibitor GKT771 decreased B16F10 melanoma cell proliferation in vitro and suppressed B16F10 tumor growth and blocked angio/lymphangiogenesis in vivo." (PMID 34943045, 2021).
melanoma (continued). "In contrast, elevated levels of superoxide dismutase (SOD) and vitamin E makes them resistant to oxidative stress while overexpression of NADPH oxidase 1 (induced by intracellular ROS) and superoxide anion are involved in malignant transformation and invasiveness of melanoma." (PMID 33624234, 2021). "In melanoma, Nox1-derived ROS sustains and Nox1 inhibition reverts EMT64." (PMID 30760703, 2019). "RAC1, a newly defined melanoma oncogene, is shown to enhance NOX1 activity." (PMID 29342889, 2018). "Gentian violet, a NOX1 inhibitor, showed promising effects in the palliation of a melanoma patient." (PMID 29118897, 2017). "To develop effective treatment options, we have examined the effect of honokiol, a phytochemical from Magnolia plant, on the migratory potential of human melanoma cell lines (A375, Hs294t, SK-Mel119 and SK-Mel28) and assessed whether Nox1 is the target." (PMID 26760964, 2016). "We observed reduced tumor vascularization in NOX1-deficient animals with B16F0 melanoma but not with LLC1 tumors." (PMID 21326871, 2011). "Among the NOX family, NOX1 and NOX4 isoforms play a major role in melanoma, while NOX5 is also important but still scarcely studied." (PMID 35326089, 2022). "Taken together, these results indicate that the specific NOX1 inhibitor GKT771 suppressed tumor growth and blocked angiogenesis and lymphangiogenesis in melanoma and colorectal syngeneic cancer models." (PMID 31249132, 2019). "Recent understanding of melanoma photobiology has implied the etiological role of NOX enzymes, particularly NOX1 and NOX4." (PMID 29342889, 2018). "Nox1 is one of several isoforms of NADPH complex; therefore, we further determined the total NADPH oxidase (Nox) activity in all the melanoma cell lines using the Nox Activity Assay Kit." (PMID 26760964, 2016). "Overexpressed levels of two isoforms of NADPH oxidase (NOX) are active in producing high ROS levels in melanoma: NOX4 and NOX1." (PMID 27756874, 2016). "The role of honokiol in inhibition of cell migration through inhibition of Nox1 expression and NADPH oxidase activity is also supported by the action of DPI in melanoma cells." (PMID 26760964, 2016). "Our data show that honokiol not only reduces the Nox1 expression or NADPH oxidase activity, but also oxidative bursts in melanoma cells." (PMID 26760964, 2016). "Therefore, we investigated the potential effect of NOX1 and ADAM17 inhibition on the generation of sMCAM by mouse melanoma and CRC cells." (PMID 38137406, 2023). "Other notable recent examples include: the significantly slower growth of the Nox1 expressing B16‐F10 melanoma and MC38 colorectal cells in Nox1‐knockout mice, and the 87% reduction in mean size of OPN‐expressing MC38 tumors in OPN‐knockout mice." (PMID 32923989, 2020). "The honokiol-mediated inhibition of Nox1 through its inhibitory effect on oxidative burst in melanoma cells and subsequently its anti-cell migration property is supported by the action of NAC in melanoma cells." (PMID 26760964, 2016). "Nox1, a catalytic subunit of NADPH oxidase, is overexpressed in melanoma." (PMID 26760964, 2016). "Western blot analysis revealed that the expression of Nox1 protein in liver, lung, kidney and spleen was greater in mice which were injected with melanoma cells compared to the mice which were not injected with melanoma cells." (PMID 26760964, 2016). "The levels of Nox1 activity were significantly higher (P<0.001) in liver, kidney and lungs compared to those detected in normal tissue samples from mice that were not injected with melanoma cells." (PMID 26760964, 2016). "In addition, we used a melanoma model because melanoma cells tend to express low levels of NOX1 (data not shown) and may not respond to NOX1 inhibition." (PMID 31249132, 2019).
Hyperglycemia (18 papers, 2013 to 2026). An increased concentration of glucose in the blood. "DNA at the Rac1 promoter region (a key subunit of Nox1/2) undergoes methylation in response to hyperglycaemia within retinal ECs and is associated with increased Nox expression and activity." (PMID 34571964, 2021). "Another report shows hyperglycemia upregulates NOX1, NOX2, NOX4, and iNOS expression in VSMC and cell migration." (PMID 39765782, 2024). "Hyperglycemia activates NOX1 and ROS production, which participates in mesangial fibrogenesis via iNOS induction." (PMID 39765782, 2024). "Human aortic endothelial cells exposed to hyperglycaemia showed increased expression of Nox1, oxidative stress and proinflammatory markers in a Nox1-siRNA reversible manner." (PMID 34571964, 2021). "It was found that human aortic endothelial cells subjected to hyperglycemia show increased NOX1 expression and increased ROS production, while the use of a NOX1 inhibitor reduces ROS production, the expression of adhesion molecules, and the infiltration of the vessel wall by inflammatory cells." (PMID 40227238, 2025). "Interestingly, hyperglycemia and/or aging induces ROS from NOX1 that forms a positive feedback loop with IL6 in both in human and murine endothelial cells." (PMID 40023978, 2025). "Hyperglycemia, a condition that characterizes DM, activates the generation of reactive oxygen species (ROS) in mitochondria and angiotensin-II-mediated activation of NADPH oxidase 1 (NOX1) and NADPH oxidase 2 (NOX 2)." (PMID 38892018, 2024). "A significant increase in the mRNA and protein levels of Nox1 (mRNA ≈ 3-fold; protein ≈ 2-fold), Nox2 (mRNA ≈ 2-fold; protein ≈ 2.7-fold), and Nox4 (mRNA ≈ 4-fold; protein ≈ 1.85-fold) isoforms were determined in the kidney of diabetic mice after 4 weeks of hyperglycaemia." (PMID 34572988, 2021). "As the complete deterioration of β-cell function occurs in advanced T2D, the data in animal models of dysregulated hyperglycemia suggest that chronic hyperglycemia may result in excess NOX1-derived superoxide and uncoupled eNOS, thereby attenuating NO production and endothelium-dependent dilation." (PMID 31382355, 2019). "Furthermore, the oxidative stress markers Nox1, Nox2, Nox4, and p47 in mRNA level were increased in DF, and consequently, it was suggested that oxidative stress is elevated in the gingival tissue by hyperglycemia." (PMID 29267310, 2017). "Hyperglycemia amplified PLY-enduced EC barrier disruption and intracellular calcium and these effects were mitigated by NOX1 inhibition and silencing (p < 0.05)." (PMID 41897422, 2026). "Exposure to hyperglycemia, the expression of NOX4 in mouse proximal renal tubular cells is increased, using NOX1/4 inhibitors (GKT136901) or NOX4 siRNA could block the damage of hyperglycemia to kidney, and reduce the production of proteinuria." (PMID 35645822, 2022). "In support of a link between hyperglycemia and NOX1, only mRNA and protein expression of NOX1, but not NOX2 or NOX4, increased with high glucose." (PMID 31382355, 2019). "Furthermore, the upregulation of NOX1 by hyperglycemia induced activation of the TLR2/NF-κB pathway both in vitro and in vivo, whereas these effects were significantly attenuated with NOX1 gene silencing and further enhanced with NOX1 gene overexpression." (PMID 36225554, 2022). "Hyperglycemia induces NOX4, p22phox, p47phox, but not NOX1 or NOX2, selectively in the renal cortex." (PMID 39765782, 2024). "In HMVEC, gene expression of SOD1 and SOD2 (non-significant) simultaneously increased with O2 ̅ levels, and CYBA (non-significant), NOX1, and NOX4 expression during hyperglycemia." (PMID 24093550, 2013).
Stroke (14 papers, 2010 to 2024). Sudden impairment of blood flow to a part of the brain due to occlusion or rupture of an artery to the brain. "Although the major protective effects are from NOX 2 or NOX4 inhibition, a study with NOX1 inhibition by Adeno-associated virus (AAV) containing NOX1 short hairpin RNA (shRNA) showed decreased peri-infarct after stroke." (PMID 34067012, 2021). "Similarly, NOX2 and NOX4 positively contribute to vascular remodeling after stroke, whereas NOX1 is recognized as a key regulator of oxidative damage in post-stroke neurogenesis, with its modulation being associated with improved functional recovery." (PMID 39334724, 2024). "One should also keep in mind that NOX1- and p47phox deficient mice had reduced basal blood pressures and blunted pressor responses to angiotensin II, which may interfere with stroke outcome." (PMID 22625431, 2012). "Since then, this paradigm has been tested in numerous models using small molecules and Nox1-, Nox2-, and Nox4-deficient mice, resulting in different outcomes and leading to disputes whether Nox2 or Nox4 isoform is the key pharmacological target for stroke." (PMID 25617620, 2015). "In addition, Nox1 mRNA expression in the brain was reported to be unchanged after 2 h MCAo in ApoE deficient mice, and we ourselves were not able to detect relative changes in Nox1 mRNA levels for up to 7 days after stroke in rats." (PMID 24961415, 2013). "Recovery outcomes were evaluated over 4 weeks using parallel bar walking tests, and the reduction in NOX1 expression was shown to positively influence post-stroke functional recovery." (PMID 39334724, 2024). "The outcomes were measured between 24 h and 4 weeks post-stroke, focusing on the roles of NOX1, NOX2, and NOX4 in the recovery process." (PMID 39334724, 2024). "To understand these mechanisms better, we need to determine the mechanism of Nox1 activation and regulation in neuronal damage after stroke." (PMID 25617620, 2015). "Although few studies have reported a role for Nox1 in experimental stroke, we recently reported a moderate reduction in lesion volume and cerebral edema, and ameliorated BBB leakage with relatively mild ischemic damage after the knockout of Nox1." (PMID 25617620, 2015). "We demonstrated, for the first time to our knowledge, that the expression of the Nox1 isoform is elevated in the peri-infarct region after stroke." (PMID 25617620, 2015). "Studies have shown NOX1 to have a protective role in ischaemic injury in experimental stroke with NOX1 KO mice displaying a four-fold greater cortical infarct volume than WT mice." (PMID 26785066, 2014). "They reported a 55% smaller stroke lesion that was paralleled by better neurological outcome in NOX1 KO versus littermate WT mice after 1 h of ischemia and 23 h of reperfusion." (PMID 22625431, 2012). "NOX1 inhibition via RNA interference in a stroke model significantly improved motor function recovery, demonstrating the potential of targeting NOX1 to mitigate post-stroke damage." (PMID 39334724, 2024). "Our data suggest that Nox1 may be involved in oxidative stress and neuronal death in the peri-infarct region after stroke." (PMID 25617620, 2015). "Few studies have addressed the role of Nox1 in experimental stroke." (PMID 25617620, 2015). "There are conflicting reports regarding the role of NOX1 in experimental stroke." (PMID 26785066, 2014). "In summary, it is unlikely that NOX1 plays a major role in stroke in mice." (PMID 22625431, 2012). "A second group observed the opposite effects of NOX1 KO on stroke." (PMID 22625431, 2012). "Results on the role of NOX1 in stroke using NOX1 KO mice are conflicting." (PMID 22625431, 2012). "However, the role of neuronal Nox1 activation in stroke is not well understood." (PMID 25617620, 2015).